TRGV7 (T cell receptor gamma variable 7 (pseudogene))
Synonyms: V1S7P; TCRGV7
Gene: T-cell receptor variable (V) pseudogene on chromosome 7 (38,335,041 to 38,335,514, reverse strand). Ensembl gene ENSG00000249978.
Diseases named in the same sentence as TRGV7 in open-access papers:
TRGV7 is named in the same sentence as 2 diseases in open-access papers, as found by Europe PMC text mining. Sharing a sentence is not in itself a finding about the gene and the disease. The quoted sentences say what the papers report.
tumor (2 papers, 2023 to 2024). "The expression of Trgv1, the gene encoding T cell receptor Vγ1 chain, but not Trgv4, Trgv5, Trgv6 or Trgv7 was also upregulated in tumours of Vil Apc Dock2 mice." (PMID 39242821, 2024).
TRGV7 also shares sentences with these, for which no sentence is quoted: prostate tumors (1 paper).